CDKN1C (cyclin dependent kinase inhibitor 1C)
Diseases named in the same sentence as CDKN1C in open-access papers (continued):
Sharing a sentence is not in itself a finding about the gene and the disease.
IMAGe syndrome (31 papers, 2013 to 2025). IMAGe syndrome is characterized by the association of intrauterine growth retardation, metaphyseal dysplasia (and short limbs), adrenal hypoplasia congenita, and genital anomalies. "It is noteworthy that both Beckwith‐Wiedemann syndrome (BWS) and IMAGe syndrome have been associated with mutations in the CDKN1C gene." (PMID 41218602, 2025). "This case expands the genetic spectrum of IMAGe syndrome by reporting a novel intronic CDKN1C variant." (PMID 41218602, 2025). "This case broadens the genetic spectrum of IMAGe syndrome by identifying the first reported intronic CDKN1C variant associated with this condition." (PMID 41218602, 2025). "Karyotype analysis confirmed a normal 46, XX karyotype without structural abnormalities, supporting the clinical diagnosis of IMAGe syndrome driven by the CDKN1C variant." (PMID 41218602, 2025). "IMAGe syndrome, a rare disorder caused by maternally inherited CDKN1C pathogenic variants, is characterized by intrauterine growth retardation (IUGR), metaphyseal dysplasia, adrenal hypoplasia congenita, and genitourinary abnormalities." (PMID 41218602, 2025). "A novel intronic CDKN1C variant (c.787+4A>T) was identified in an Iranian girl with IMAGe syndrome, expanding its genetic spectrum." (PMID 41218602, 2025). "This case report describes a 5‐year‐old Iranian girl with IMAGe syndrome associated with a novel intronic CDKN1C variant (c.787+4A>T), the first such variant linked to this condition, expanding its genetic spectrum." (PMID 41218602, 2025). "CDKN1C mutations cause intrauterine growth restriction, metaphyseal dysplasia, adrenal hypoplasia congenita, and genital abnormalities syndrome (OMIM:300290) and Beckwith–Wiedemann syndrome (OMIM:600856)." (PMID 39886673, 2024). "The IMAGE syndrome is usually caused by heterozygous missense variants in the negative cell cycle regulator, cyclin-dependent kinase inhibitor 1 C (CDKN1C)." (PMID 36255414, 2023). "Most individuals with IMAGe syndrome carry pathogenic variants in cyclin-dependent kinase inhibitor 1C (CDKN1C/p57), a negative regulator of cell proliferation." (PMID 33477564, 2021). "Classic IMAGe syndrome is associated with gain-of-function variants in the cell-cycle repressor, CDKN1C." (PMID 33381483, 2020). "IMAGE syndrome (OMIM #614732) results from a gain-of-function mutation in the CDKN1C gene, negatively regulating cellular proliferation." (PMID 30968677, 2020). "Since CDKN1C is expressed only from the maternal allele, IMAGE syndrome occurs only when the CDKN1C gain-of-function mutation is inherited from the mother." (PMID 30968677, 2020). "Pathogenic CDKN1C gain-of-function variants on the maternal allele were initially reported as a cause of IMAGe syndrome characterized by intrauterine growth retardation, metaphyseal dysplasia, primary adrenal insufficiency and genital anomalies." (PMID 33076988, 2020). "The syndromic category includes four different forms which are AAA syndrome (AAAS mutations), IMAGE syndrome (CDKN1C mutations), MIRAGE syndrome (SAMD9 mutations), and a syndrome with MCM4 mutations." (PMID 31208161, 2020). "To date, children with IMAGe syndrome have all been found to harbour pathogenic single nucleotide variants (SNVs) in a very specific region of the PCNA-binding domain of CDKN1C (Arboledaet al., 2012;Cabrera-Salcedoet al., 2017)." (PMID 31497289, 2019). "It is present within the PCNA‐binding domain of the CDKN1C protein, where pathogenic variants have previously been associated with IMAGe syndrome or with a RSS‐like phenotype." (PMID 31976094, 2019). "In contrast,gain-of-function variants in CDKN1C have been shown to cause growth restriction as part of IMAGe syndrome (OMIM 614732) (Arboledaet al., 2012)." (PMID 31497289, 2019). "A similar growth restriction condition causing adrenal hypoplasia is IMAGe syndrome, due to gain-of-function changes in the paternally imprinted cell cycle regulator CDKN1C." (PMID 28346228, 2017).
IMAGe syndrome (continued). "Mutations in the CDKN1C coding region have been observed in some patients with an IMAGe syndrome (MIM 614732), another complex growth restriction disorder whose early clinical features, including IUGR, overlap with that of SRS." (PMID 27798108, 2016). "The data presented here give the further direct evidence of how the PCNA-binding site mutations in CDKN1C affect the cell cycle and cause IMAGe syndrome." (PMID 25861374, 2015). "IMAGe syndrome is caused by gain-of-function missense mutations in the CDKN1C region encoding the PCNA-binding domain (amino acids 271-279) of the maternal allele, which cause loss of PCNA binding and pathogenic CDKN1C gain of function." (PMID 25541901, 2014). "We identified a novel heterozygous mutation, c.815T>G (p.Ile272Ser), in the CDKN1C gene in three siblings manifesting clinical symptoms associated with IMAGe syndrome and their mother (unaffected carrier)." (PMID 24098681, 2013). "In the present study, we identified a novel maternally inherited mutation in the PCNA-binding domain of the CDKN1C gene in three siblings manifesting symptoms associated with IMAGe syndrome." (PMID 24098681, 2013). "We report a novel intronic CDKN1C variant in a 5‐year‐old Iranian girl with IMAGe syndrome." (PMID 41218602, 2025). "Notably, the mutational status of CDKN1C assumes remarkable relevance, especially for IMAGe syndrome where the clinical diagnosis is established through the identification of a missense variant in the maternal CDKN1C gene." (PMID 34299047, 2021). "The rare IMAGe syndrome, which has the major features of fetal growth restriction, metaphyseal displasia, adrenal hypoplasia congentia and genital abnormalities, is associated with genetic mutations in the CDKN1C gene." (PMID 26963625, 2016). "Recently, our group described gain-of-function mutations in the PCNA-binding site of CDKN1C that result in an undergrowth syndrome called IMAGe Syndrome (Intrauterine Growth Restriction, Metaphyseal dysplasia, Adrenal hypoplasia, and Genital anomalies), with life-threatening consequences." (PMID 25861374, 2015). "However, loss of PCNA binding and suppression of CDKN1C monoubiquitination by IMAGe-associated mutations hardly explain the reduced-growth phenotype characteristic of IMAGe syndrome." (PMID 24098681, 2013). "Finally, this work may have also have implications for the imprinting disorders Beckwith–Wiedemann, Silver–Russell and iMAGE syndromes that are associated with altered CDKN1C dosage." (PMID 28857482, 2018). "Genetic testing targeting CDKN1C is critical for suspected IMAGe syndrome cases, and further studies are needed to confirm the functional impact of intronic variants." (PMID 41218602, 2025). "The maternal inheritance and paternal imprinting observed in this case align with CDKN1C's known expression pattern, supporting its role in IMAGe syndrome pathogenesis." (PMID 41218602, 2025). "CDKN1C is already known to cause BWS (LoF variants), IMAGe syndrome (PCNA domain GoF variants), and an atypical version of RSS." (PMID 31976094, 2019). "Constitutional growth restriction associated with both IMAGe syndrome and SRS have been reported in rare patients with gain-of-function mutations in the CDKN1C PCNA domain that presumably alters protein clearance by the ubiquitin-proteasome." (PMID 27200075, 2016). "In vivo models have showed that mouse embryonic growth is sensitive to the precise dosage of Cdkn1c and excess of this protein results in dose dependent embryonic growth retardation, a phenotype seen in patients with IMAGe Syndrome." (PMID 25861374, 2015). "Mutations in the proliferating cell nuclear antigen (PCNA)-binding domain of the CDKN1C gene were recently identified in patients with IMAGe syndrome." (PMID 24098681, 2013). "Specifically, loss‐of‐function mutations in the CDKN1C gene have been implicated in the pathogenesis of 5%–10% of BWS patients, while gain‐of‐function mutations in this gene have been linked to IMAGe syndrome." (PMID 41218602, 2025).
IMAGe syndrome (continued). "Furthermore, FGR is a key feature of specific conditions such as MIRAGE syndrome (SAMD9) and IMAGe syndrome (CDKN1C)." (PMID 36419940, 2022). "Interestingly, loss-of-function variants of CDKN1C lead to an overgrowth syndrome, whereas gain-of-function variants localizing to the PCNA binding domain of CDKN1C cause IMAGe syndrome." (PMID 33477564, 2021). "Mutations of the PCNA domain of the CDKN1C gene are known to be associated with IMAGe syndrome thus with adrenal disease, although neither affected patient in our case had evidence of adrenal dysfunction." (PMID 31976094, 2019). "A1’s mother had normal stature with no features in keeping with RSS/IMAGe syndrome, although she did carry the CDKN1C variant." (PMID 31976094, 2019). "The CDKN1C related atypical RSS though within the mutational hotspot region of the IMAGe syndrome it does not exhibit adrenal insufficiency nor metaphyseal dysplasia as reported in the literature thus far." (PMID 31976094, 2019). "Elevated expression of Cdkn1c has been implicated as a cause of two similar but distinct childhood growth restriction disorders, Silver–Russell (SRS) and IMAGe syndrome, while a loss-of-function of Cdkn1c is present in familial cases of the childhood overgrowth disorder Beckwith–Wiedemann syndrome." (PMID 30213134, 2018). "We hypothesize that IMAGe syndrome mutations result in loss of PCNA-binding and a gain-of-function of CDKN1C." (PMID 25861374, 2015). "Therefore, an increase in the CDKN1C protein level can easily lead to the typical gain-of-function phenotypes observed in IMAGe syndrome patients." (PMID 24098681, 2013). "The G1-phase cell-cycle inhibition is increased due to increased stability of CDKN1C IMAGe mutants, which maintains an intact cyclin-dependent kinase binding domain, resulting in decreased proliferation and the undergrowth phenotype observed in patients with IMAGe syndrome." (PMID 25861374, 2015). "A possibility of IMAGe syndrome was considered, but we could not find any mutations in the CDKN1C gene." (PMID 25541901, 2014). "Neither de novo mutation nor germline mosaicism has been reported, but both are possible, since CDKN1C mutation-negative IMAGe syndrome patients may have mutant genes that can be related to signal transduction pathway involving CDKN1C." (PMID 25541901, 2014). "There is now sufficient evidence from animal models and human studies to indicate a key role for the imprinted CDKN1C gene in SRS, BWS and IMAGe syndrome." (PMID 26963625, 2016). "Deciphering the role of these putative enhancer elements in regulating tissue-specific expression of CDKN1C will be important to understand the molecular etiologies of non-syndromic IUGR, SRS, BWS, and IMAGe syndrome." (PMID 27200075, 2016). "This novel analysis pipeline identified a single mutation, NM_000076.2:c.832A>G (p.Lys278Glu) in the imprinted gene CDKN1C (OMIM 600856), and provided the diagnosis of IMAGe syndrome for the proband." (PMID 25614875, 2014). "Given concerns about GH therapy's potential cancer risks and CDKN1C's association with malignancies in BWS, caution is warranted, though no malignancy link is established for IMAGe syndrome beyond a single rhabdomyosarcoma case." (PMID 41218602, 2025). "The severity of intrauterine growth restriction in IMAGe syndrome reported in the literature ranged from − 2.5 to − 3.8 birth weight SDS and was not different to SRS caused by CDKN1C mutations with a range from − 2.5 to − 5.2 birth weight SDS." (PMID 33076988, 2020). "We consider that metaphyseal dysplasia might not be an essential component of IMAGe syndrome, although CDKN1C might play a role in bone disorders because CDKN1C knockout mice present with several bone anomalies." (PMID 24098681, 2013).
gastric cancer (23 papers, 2011 to 2025). A primary or metastatic malignant neoplasm involving the stomach. "Thus, up-regulation of CDKN1A was associated with cervical cancer and down-regulation of CDKN1C with gastric cancer." (PMID 32887258, 2020). "PRMT5 interacts with c-Myc and inhibits PTEN, CDKN2C (p18INK4C), CDKN1A (p21CIP1 or WAF1), CDKN1C (p57KIP2), and p63 gene expression to promote gastric cancer cell growth." (PMID 41154773, 2025). "Further study demonstrated that CDKN1C (p57Kip2) was the potential downstream gene of regulated by NSUN2 in gastric cancer." (PMID 32332707, 2020). "miR21 downregulates CDKN1C in prostate cancer, miR25 in gastric cancer and glioma and miR92b in brain tumors." (PMID 29614816, 2018). "Moreover, NSUN2 fuels gastric cancer cell proliferation by repressing CDKN1C in an m5C‐dependent manner." (PMID 37228185, 2023). "In addition, there have been reports that NSUN2 is significantly up‐regulated in gastric cancer, inhibits the expression of CDKN1C in an m5C‐dependent manner and promotes the proliferation of gastric cancer cells." (PMID 33400376, 2021). "In this study, we found that c-Myc could interact directly with PRMT5 to transcriptionally repress the expression of a cohort of genes, including PTEN, CDKN2C (p18INK4C), CDKN1A (p21CIP1/WAF1), CDKN1C (p57KIP2) and p63, to promote gastric cancer cell growth." (PMID 32292506, 2020). "We obtained 43 DEGs with the adjusted p < 0.05 and | log2 FC)|>1, of which JUNB, ID1, CDKN1C, ID3, and BCAR3 were lowly expressed in gastric cancer tissues, and the remaining DEGs were highly expressed in gastric cancer tissues." (PMID 36467074, 2022). "For example, expression of CDKN1C, RASSF7, GPRC5A, and MPZL2 were all significantly related to KLF5 in gastric cancer tissue." (PMID 33923166, 2021). "Additionally, in gastric cancer (GC), NSUN2 modifies the 3'UTR of cyclin-dependent kinase inhibitor 1C (CDKN1C, p57Kip2) mRNA to repress its stability, decreasing the half-life of p57Kip2 mRNA." (PMID 35562754, 2022).
intrauterine growth restriction (20 papers, 2013 to 2025). "Plagl1 was previously shown to regulate expression of Cdkn1c, Igf2, H19, and Dlk1 and to belong to a subset of IGs that control embryonic growth and differentiation, and loss of Plagl1 function resulted in intrauterine growth restriction." (PMID 36437415, 2023). "Here we describe a novel mutation in the PCNA-binding domain of the CDKN1C gene in three Japanese siblings who manifest most of the IMAGe-associated symptoms: i.e., intrauterine growth restriction, adrenal hypoplasia congenita, and genital anomalies in males." (PMID 24098681, 2013). "Increased CDKN1C mRNA levels have been observed in cases of the intrauterine growth restriction in both mice and human." (PMID 38228612, 2024). "Consistently, it has been reported that the mRNA levels of PHLDA2 and CDKN1C were increased whereas the IGF-2 mRNA levels were decreased in human intrauterine growth restriction (IUGR) placentas." (PMID 31194812, 2019). "It would now seem pertinent to examine BAT in SRS patients and, conversely, to assess individuals with a diagnosis of fetal growth restriction followed by extreme thinness for alterations in the expression of CDKN1C." (PMID 26963625, 2016). "The atypical presence of fetal growth restriction in the newborn and the absence of CDKN1C gene mutations have not been reported to date in BWS." (PMID 37686168, 2023). "The CDKN1C gene is expressed at higher levels in the placenta compared to adult tissues, which suggests that it may play a role in the development of fetal growth restriction (FGR) and supports the hypothesis that it is involved in the maintenance of pregnancy." (PMID 41218602, 2025). "Fetal growth restriction per se is a relatively generic phenotype and more specific features of SRS would lend greater support to the hypothesis that altered expression of CDKN1C contributes significantly to SRS in human patients." (PMID 26963625, 2016). "While fetal growth restriction and low birth weight are relatively common complications of pregnancy that can have numerous origins, the more specific features of SRS support a major role for elevated CDKN1C expression in SRS." (PMID 26963625, 2016). "More recently, SNVs in the PCNA-binding domain of CDKN1C have been reported in families with maternally-inherited fetal growth restriction (FGR)without adrenal insufficiency and in familial Silver-Russell syndrome (SRS) (OMIM180860) (Brioudeet al., 2013;Kernset al., 2014;Sabiret al., 2019)." (PMID 31497289, 2019).
pancreatic cancer (18 papers, 2008 to 2025). "Decreased CDKN1C mRNA expression due to several mechanisms has recently been described in primary pancreatic neoplasms." (PMID 18325103, 2008). "Also, update research has highlighted that EZH2-mediated H3K27m3 blockade of cyclin-dependent kinase inhibitor 1C could suppress glycolysis, proliferation and migration of pancreatic cancer cells." (PMID 35414117, 2022). "BLACAT1 inhibits the trimethylation of H3K27 on the CDKN1C gene by blocking the recruitment of EZH2, thereby promoting the expression of CDKN1C and inhibiting the expression of CCNE, and thus suppressing the biological processes of pancreatic cancer cells." (PMID 40778223, 2025). "Most remarkably, CDKN1C has been reported as one of the most under-expressed genes at both the RNA and protein level, in a set of intraductal papillary mucinous neoplasm (IPMN) of the pancreas, and in several pancreatic cancer cell lines." (PMID 38877560, 2024).
hepatocellular carcinoma (13 papers, 2011 to 2024). A malignant tumor that arises from hepatocytes. "m5C writer NSUN2 acts as an oncogene to promote gastric cancer and hepatocellular carcinoma (HCC) development by regulating protein-encoding gene CDKN1C and lncRNA H19, respectively." (PMID 36806253, 2023). "Similar inverse correlations between Kcnq1ot1 and CDKN1C expression were observed in three hepatoma cell lines, indicating a diverse and complex bidirectional regulatory role for lncRNAs in tumorigenesis." (PMID 26378581, 2015). "In human hepatocellular carcinoma cells, miR-221-3p was found to control cyclin-dependent kinase inhibitor 1B (p27Kip1) and cyclin-dependent kinase inhibitor 1C (p57Kip2) expression." (PMID 25052466, 2014). "Likewise, in hepatocellular carcinoma cells (HCC), Arnt up-regulates CDKN1C, a gene that is also regulated by the Myc/Miz-1 complex." (PMID 24618291, 2014). "Additionally, HES1 is a direct negative transcriptional regulator of CDKN1C in hepatocellular carcinoma cells." (PMID 36037042, 2022).